APPAT (atherosclerotic plaque pathogenesis associated transcript)
Synonyms: AC092683.1; formerly LINC02969
Gene: Long non-coding RNA gene on chromosome 2 (97,416,059 to 97,437,397, reverse strand). Ensembl gene ENSG00000230606.
Diseases named in the same sentence as APPAT in open-access papers:
APPAT is named in the same sentence as 9 diseases in open-access papers, as found by Europe PMC text mining. Sharing a sentence is not in itself a finding about the gene and the disease. The quoted sentences say what the papers report.
atherosclerosis (3 papers, 2018 to 2020). A disease characterized by the build-up of fatty material and calcium deposition in the arterial wall resulting in partial or complete occlusion of the arterial lumen. "The level of APPAT in extracellular circulating blood was investigated for whether it was detectable in blood sample, as well as existence of any dysregulation in atherosclerosis pathophysiologic process." (PMID 29372117, 2018).
angina pectoris (1 paper, 2018). The symptom of paroxysmal pain consequent to MYOCARDIAL ISCHEMIA usually of distinctive character, location and radiation. "We also assessed the level of circulating APPAT in blood samples from healthy individuals, and patients with angina pectoris (AP) or myocardial infarction (MI)." (PMID 29372117, 2018).
coronary artery stenosis (1 paper, 2018). "Together with the down-regulation in coronary artery of CAD patient, we inferred that APPAT possibly plays key role in maintaining phenotype of VSMCs in disease progression, thus influencing the severity of coronary artery stenosis, especially the vulnerable plaque stability." (PMID 29372117, 2018).
APPAT also shares sentences with these, for which no sentence is quoted: Hypertension (2 papers); aortic aneurysm (1); cardiovascular disease (1); coronary heart disease (1); diabetes (1); myocardial infarction (1).